AFP (alpha fetoprotein)
Diseases named in the same sentence as AFP in open-access papers (continued):
Sharing a sentence is not in itself a finding about the gene and the disease.
COVID-19 (1 paper, 2022). A disease caused by infection with severe acute respiratory syndrome coronavirus 2. "High levels of AFP are also indicative of a patient with chronic liver disease and patients with such an existing condition usually have bad prognosis for COVID-19 as well." (PMID 36094909, 2022). "The elevation of most serum cancer biomarkers correlates with severity of COVID-19 except AFP." (PMID 36094909, 2022).
Cushing syndrome (1 paper, 2017). Cushing's syndrome (CS) encompasses a group of hormonal disorders caused by prolonged and high exposure levels to glucocorticoids that can be of either endogenous (adrenal cortex production) or exogenous (iatrogenic) origin. "However, in a 10-year-old boy with pancreatic acinar cell tumor, Cushing’s syndrome, which was diagnosed with high serum adrenocorticotropic hormone and cortisol levels, was identified with the tumor, and excessive AFP level in serum was observed." (PMID 29206210, 2017).
cystic tumor (1 paper, 2026). "After induction and salvage chemotherapy, AFP levels decreased to 20 ng/mL but did not normalize, and a 55-mm cystic tumor persisted." (PMID 41797852, 2026).
Dandy-Walker malformation (1 paper, 2018). "The pregnancy was complicated by spotting, sub chorionic hemorrhage, elevated maternal serum alpha-fetoprotein (MSAFP), possible Dandy-Walker malformation (DWM) with bilateral ventriculomegaly, unilateral ureteral dilation, and fetal macrosomia." (PMID 30385778, 2018).
duodenal adenocarcinoma (1 paper, 2024). A carcinoma that arises from glandular epithelial cells of the duodenum. "Recently, an autopsy case about an AFP-producing large duodenal adenocarcinoma was published with a significantly high level of AFP (42,078.4 ng/ml)." (PMID 38817451, 2024).
duodenal carcinomas (1 paper, 2024). "Overall, 21 AFP-producing duodenal carcinomas have been documented." (PMID 38817451, 2024).
endometrial neoplasm (1 paper, 2021). Tumors or cancer of ENDOMETRIUM, the mucous lining of the UTERUS. "Third, recognizing the category of AFP+ EC would make the classification of AFP-producing endometrial neoplasms more consistent with classifications of tumors in other organs, such as stomach and lung." (PMID 34977100, 2021).
epidermal cyst (1 paper, 2017). "In this study, elevated AFP was detected in 6 children, and 5 of them underwent radical orchiectomy, while the other one had typical ultrasound characteristics of an epidermal cyst." (PMID 28347316, 2017). "One child with an epidermal cyst had an AFP level of 76.2 μg/L." (PMID 28347316, 2017).
epilepsy (1 paper, 2019). A brain disorder characterized by episodes of abnormally increased neuronal discharge resulting in transient episodes of sensory or motor neurological dysfunction, or psychic dysfunction. "Additionally, while extrinsic factors in an infant’s sleep environment are typically noted, features that may influence underlying biologic processes often do not receive attention (smoking during pregnancy, in utero alpha-fetoprotein levels, brainstem serotonin levels, epilepsy in-situ)." (PMID 31502215, 2019).
erythrocytosis (1 paper, 2024). "A subgroup analysis based on a paraneoplastic syndrome revealed significant differences in patients with erythrocytosis compared to those without paraneoplastic syndromes in terms of tumor size, albumin, and AFP levels (p < 0.001)." (PMID 38674198, 2024).
female infertility (1 paper, 2020). Diminished or absent ability of a female to achieve conception. "Several studies have found that AFP is associated with female infertility and that AFP deficiency in mice causes dysfunction of the hypothalamus-pituitary axis and anovulation." (PMID 33009373, 2020).
gastroesophageal junction adenocarcinoma (1 paper, 2025). A carcinoma that arises from glandular epithelial cells of the esophagogastric junction. "A phase II, multi-center, single-arm clinical study (NCT04609176) enrolled 36 patients with stage III-IV unresectable or metastatic gastric or gastroesophageal junction adenocarcinoma, whose AFP levels were more than twice the upper normal limit." (PMID 40999892, 2025).
gestational trophoblast diseases (1 paper, 2022). "Whether AFP can be used as the only trackable indicator for evaluating the therapeutic effect of vaginal YSTs, such as β-human chorionic gonadotropin, in gestational trophoblast diseases, remains to be determined." (PMID 36452350, 2022).
granulosa cell tumor (1 paper, 2025). A slow-growing, malignant tumor, characterize by the presence of granulosa-like cells and Call-Exner bodies, that is almost always found in the ovary. "In young patients, BGCS and ESGO recommend an extended panel including AFP, β-hCG, LDH, Inhibin B, and AMH to detect germ cell or granulosa cell tumors." (PMID 41463165, 2025).
Gynecomastia (1 paper, 2019). Abnormal development of large mammary glands in males resulting in breast enlargement. "Systemic manifestations such as gynecomastia can be caused by beta-hCG; therefore, assaying serum beta-HCG, AFP, and LDH is essential to preventing diagnostic delay of a GCT in patients presenting with extra-gonadal symptoms." (PMID 31118058, 2019).
Hematochezia (1 paper, 2018). The passage of fresh (red) blood per anus, usually in or with stools. "The majority of cases presented with hematochezia and showed elevated serum AFP." (PMID 29416804, 2018).
hemihyperplasia (1 paper, 2025). "Given the association between hemihyperplasia and tumor risk, screening for neoplasms using abdominal ultrasound and serum alpha-fetoprotein testing is recommended." (PMID 40959375, 2025).
hemorrhage (1 paper, 2022). Loss of blood from the vascular compartment to the exterior or into nonvascular body space as a result of rupture or severance of the blood vessels. "In a previous study, the elevation of plasma AFP level was supposed to be able to predict pregnancy risk including feto-maternal hemorrhage." (PMID 36300123, 2022).
hepatic angiosarcoma (1 paper, 2026). "Most individuals demonstrated normal serum AFP and CA 19-9 levels, indicating limited diagnostic value of these tumor markers for hepatic angiosarcoma." (PMID 41594267, 2026).
hepatic vein thrombosis (1 paper, 2025). A condition in which the hepatic venous outflow is obstructed anywhere from the small hepatic veins to the junction of the inferior vena cava and the right atrium. "In this study, Patients who continued treatment for less than 6 months (38.43%) showed higher baseline AFP, less patients with BCLC-C than B and more prevalent hepatic vein thrombosis, extra-hepatic spread and with significantly worse OS." (PMID 40579411, 2025).
hepatocellular adenoma (1 paper, 2018). A benign epithelial neoplasm arising from the hepatocytes. "Preneoplastic lesions included α-fetoprotein (AFP) positive foci, foci of altered hepatocytes (FAH), and hepatocellular adenomas (HCA)." (PMID 30307978, 2018).
hepatoid adenocarcinoma of the bladder (1 paper, 2025). "AFP-producing hepatoid adenocarcinoma of the bladder has been reported in several cases." (PMID 40406259, 2025).
hyperlipidemia (1 paper, 2024). "Univariate analysis for OS showed that hyperlipidemia, maximum intrahepatic tumor size, several intrahepatic tumors, macrovascular invasion, AFP level, Child–Pugh score, mALBI grade, and NLR were significant factors associated with OS." (PMID 38165900, 2024). "Multivariate analysis revealed that the absence of hyperlipidemia, higher number of intrahepatic tumors, macrovascular invasion, higher AFP level, worse Child–Pugh score, and higher NLR were significantly associated with poor prognoses." (PMID 38165900, 2024).
hypertriglyceridemia (1 paper, 2025). A laboratory test result indicating elevated triglyceride concentration in the blood. "Univariate analysis showed that T2DM, HCV-MASLD, hypertriglyceridemia, hypo-HDL cholesterolemia, AST, ALT, ɤ-GTP, albumin, platelet count, FSG, HDL-C, AFP, LSM, FIB-4 index, aMAP score, and FAST score were significantly associated with HCC development." (PMID 40624408, 2025). "Since T2DM, hypertriglyceridemia, and hypo-HDL cholesterolemia are included in HCV-MASLD, multivariable analysis was conducted with HCV-MASLD, AFP, aMAP score, and FAST score." (PMID 40624408, 2025). "Univariate analysis showed that hypertriglyceridemia, Hypo-HDL cholesterolemia, AST, platelet count, AFP, LSM, FIB-4 index, aMAP score, and FAST score were significantly associated with HCC development." (PMID 40624408, 2025).
Hypertyrosinemia (1 paper, 2023). An increased concentration of tyrosine in the blood. "Serum alpha-fetoprotein levels were elevated, in parallel to hypertyrosinemia, in all patients in the Israeli Druze cohort, two Saudi patients (F3, F4), and the three Lebanese patients reported in this study." (PMID 37456661, 2023).
Hyponatremia (1 paper, 2014). An abnormally decreased sodium concentration in the blood. "In addition, clinical and standard laboratory variables were significantly different between the two groups regarding the infection rate, hyponatremia, alpha-fetoprotein (AFP), Arginine Hydrochloride use and Lactulose use." (PMID 24748895, 2014).
immunoglobulin deficiency (1 paper, 2017). "A comparison with the two previously identified patients indicates immunoglobulin deficiency, cellular radiosensitivity, and increased AFP levels as hallmarks of RNF168 deficiency." (PMID 29255463, 2017).
Inguinal hernia (1 paper, 2016). Protrusion of the contents of the abdominal cavity through the inguinal canal. "Because of the suspected diagnosis of ovarian MCT incarcerated in an inguinal hernia, serum levels of alpha-fetoprotein (AFP), beta-human chorionic gonadotropin (BHCG), and lactate-dehydrogenase (LDH) were investigated, revealing normal serum values." (PMID 27525145, 2016).
intracranial germinomas (1 paper, 2016). "To establish an appropriate cutoff value of serum β-HCG for diagnosis of intracranial germinomas, we retrospectively reviewed the records of intracranial tumor patients who received serum β-HCG and AFP tests for diagnostic purposes in our hospital during the recent 10 years." (PMID 26771195, 2016). "There are no other tumor markers better than β-HCG and AFP for now, therefore determining an optimal cutoff of serum β-human chorionic gonadotropin for assisting the diagnosis of intracranial germinomas is clinical significant." (PMID 26771195, 2016).
invasive breast carcinoma (1 paper, 2024). A carcinoma that infiltrates the breast parenchyma. "Another case was described in 2019, involving a 33-year-old female with a history of invasive breast carcinoma who was admitted to the hospital for elevated alpha-fetoprotein level." (PMID 39036154, 2024).
Leydig cell ovarian tumor (1 paper, 2024). "We presented a rare clinical case of an early-stage moderately differentiated unilateral DICER1 wild-type Sertoli–Leydig cell ovarian tumor with AFP elevation that caused amenorrhea in an adolescent patient." (PMID 39336518, 2024).
lymph node disease (1 paper, 2022). "Patients with isolated retroperitoneal lymph node disease, those with AFP-only elevation, and those who undergo complete resection of the residual disease have the most favorable outcome." (PMID 35267435, 2022).
lymphadenopathies (1 paper, 2016). "According to those reports, HAC is associated with large tumor, AFP production, poor prognosis, a predilection for older patients, regional lymphadenopathies, and distant metastases." (PMID 26943677, 2016).
lysosomal storage disorders (1 paper, 2022). "It is possible that elevated AFP levels will be found in other metabolic hepatopathies and possibly in other lysosomal storage disorders." (PMID 35455589, 2022). "Elevated AFP levels were also documented in another lysosomal storage disorder with hepatic involvement—a type-1 Gaucher patient, who developed a Gaucheroma." (PMID 35455589, 2022).
malignant ovarian germ cell tumors (1 paper, 2019). "Alpha-fetoprotein (AFP) plays a crucial role in the management of malignant ovarian germ cell tumors (MOGCTs) and is an important reference index for chemotherapy termination." (PMID 31836006, 2019).
meningocele (1 paper, 2024). A congenital abnormality in which the meninges protrude through a defect in the spinal column or the cranium. "Meningoceles are often diagnosed prenatally using methods such as ultrasound and maternal alpha-fetoprotein (AFP), while MRI is the preferred modality for pre-operative imaging and diagnostic confirmation." (PMID 38989380, 2024).
Meningomyelocele (1 paper, 2024). Congenital, or rarely acquired, herniation of meningeal and spinal cord tissue through a bony defect in the vertebral column. "The diagnosis of meningomyeloceles can be made prenatally via maternal screenings including serum levels of alpha-fetoprotein, however, the screening test of choice is a second-trimester ultrasound." (PMID 39463665, 2024).
microcephaly (1 paper, 2017). A congenital or acquired developmental disorder in which the circumference of the head is smaller than normal for the person's age and sex. "The second patient with RNF168 deficiency has been described in the literature with a somewhat different clinical phenotype including mild gait ataxia, ocular telangiectasia, elevated AFP, immunodeficiency, microcephaly, growth retardation, and terminal respiratory failure." (PMID 29255463, 2017).
multiple acyl-CoA dehydrogenase deficiency (1 paper, 2002). "Prenatal diagnosis of multiple acyl-CoA dehydrogenase deficiency associated with elevated alpha-fetoprotein and cystic renal change has been established." (PMID 12402156, 2002).
myelocystocele (1 paper, 2023). "In cases of a malignant SCT, AFP levels in amniotic fluid or maternal serum may be increased, however, terminal myelocystocele is not linked to the elevation in AFP." (PMID 40041260, 2023).
necrotizing enterocolitis (1 paper, 2024). Necrotizing enterocolitis (NEC) is a devastating disease that affects mostly the intestine of premature infants. "Postnatally, AFP may serve as a marker of gastrointestinal mucosal regeneration following intestinal surgeries for necrotizing enterocolitis (NEC) or other intestinal injuries in children." (PMID 38256600, 2024).
nephrotic syndrome (1 paper, 2024). A collection of symptoms that include severe edema, proteinuria, and hypoalbuminemia; it is indicative of renal dysfunction. "High maternal and amniotic fluid AFP levels result from protein loss due to fetal nephrotic syndrome." (PMID 38256600, 2024).
neuroendocrine tumor of the thymus (1 paper, 2023). "An alpha-fetoprotein (AFP)-positive neuroendocrine tumor of the thymus is a rare thoracic malignancy." (PMID 37721573, 2023).
Nijmegen breakage syndrome (1 paper, 2007). Nijmegen breakage syndrome is a rare genetic disease presenting at birth with microcephaly, dysmorphic facial features, becoming more noticeable with age, growth delay, and later-onset complications such as malignancies and infections. "After exclusion of the Nijmegen breakage syndrome by mutation analysis and exclusion of AT on clinical grounds (supported by normal AFP levels), sequencing of the LIG4 gene established the diagnosis of DNA ligase IV deficiency syndrome." (PMID 17224058, 2007).
ovarian immature teratoma (1 paper, 2020). "One study, which excluded patients with highly elevated AFP levels (above 1000 ng/mL), revealed that the grade was the most important risk factor for relapse in ovarian immature teratoma and adjuvant chemotherapy did not decreased relapses." (PMID 32006216, 2020).
pancreatic lymphoma (1 paper, 2025). "AFP levels in pancreatic lymphoma generally remain within the normal limits." (PMID 41347077, 2025).
Pancreatoblastoma (1 paper, 2025). A rare malignant epithelial neoplasm arising from the pancreas. "Among the 48 patients admitted to the hospital for blood examination, 9 patients with pancreatoblastoma had elevated serum AFP, and 6 patients had elevated serum direct bilirubin, ranging from 70.2 to 145.6 μmol/L." (PMID 40574954, 2025).
pericardial effusion (1 paper, 2014). Fluid collection within the pericardial sac, usually due to inflammation. "A small amount of pericardial effusion remained, but there was no effusion in the thoracic or abdominal cavities and the AFP was decreased significantly." (PMID 24396445, 2014).
placenta previa (1 paper, 2023). "The group with placenta accreta or placenta previa had a higher median AFP and β-hCG multiples of median (MoM) than the normal placentation group." (PMID 37781207, 2023). "The combination of AFP and ultrasound imaging may be used to assess the status of placenta previa." (PMID 37781207, 2023).
placental tumors (1 paper, 2024). "In placental tumors, the elevated AFP levels in maternal serum are caused by its release into both the amniotic fluid and the maternal placental circulation." (PMID 38256600, 2024).
polyneuropathy (1 paper, 2022). A disease or disorder affecting more than one nerve. "With NGS application, we identified a novel heterozygous mutation of SETX in a case of ARCA with polyneuropathy and elevated AFP without OMA in Taiwan." (PMID 35203940, 2022).
precocious puberty (1 paper, 2025). Unusually early sexual maturity. "We report a 9-year-old boy who presented with gonadotropin-independent precocious puberty characterized by suppressed gonadotropins, elevated serum testosterone, and increased hCG and alpha-fetoprotein levels." (PMID 41404345, 2025). "Laboratory evaluation revealed suppressed gonadotropins (LH <0.30 mIU/mL, FSH <0.30 mIU/mL), paradoxically elevated serum testosterone (2.05 ng/mL), and increased levels of hCG (7.6 mIU/mL) and AFP (13.3 ng/mL), findings consistent with gonadotropin-independent precocious puberty." (PMID 41404345, 2025).
prostate tumors (1 paper, 2025). "Tumor markers, including Beta-hCG, AFP, CA 19-9, CEA, and PSA, were negative, helping to exclude germ cell, gastrointestinal, and prostate tumors from the initial differential diagnosis based on the patient’s age, sex, and nodal distribution." (PMID 41492611, 2025). "Tumor markers, including Beta-hCG, AFP, CA 19-9, CEA, and PSA, were negative, helping to exclude germ cell, gastrointestinal, and prostate tumors from the differential diagnosis." (PMID 41492611, 2025).
psychosis (1 paper, 2023). "No case-control differences in FA were found for AFP and other psychosis." (PMID 36510004, 2023).
pulmonary blastoma (1 paper, 2015). A malignant neoplasm of the lung composed of tubular structures and immature mesenchymal elements, which may differentiate towards skeletal and smooth muscle, cartilage or a combination of muscle and cartilage. "In the present case, the treatment after the 3 courses showed decreased levels of AFP and decreased tumor size of the metastasis, suggesting that this regimen is effective on biphasic pulmonary blastoma." (PMID 26075125, 2015). "In particular, AFP positive tumor cells are seen in many pulmonary blastoma cases." (PMID 26075125, 2015). "Therefore, an elevated level of AFP in a patient with lung tumor is one of suggestions to suspect pulmonary blastoma." (PMID 26075125, 2015).
renal carcinoma (1 paper, 2020). A carcinoma arising from the epithelium of the renal parenchyma or the renal pelvis. "We concluded that AhR ligand antitumor agents, such as AFP 464 and 5F 203, represent potential new candidates for the treatment of renal cancer." (PMID 32443455, 2020).
respiratory failure (1 paper, 2021). The significant impairment of gas exchange within the lungs resulting in hypoxia, hypercarbia, or both, to the extent that organ tissue perfusion is severely compromised. "Multisystem involvement, including immunocompromised states, progressive respiratory failure, radiosensitivity, oculocutaneous telangiectasia, and an increased risk of malignancy with elevated serum alpha fetoprotein (AFP) levels, leads to complications." (PMID 34404412, 2021).